PRKCE (protein kinase C epsilon)
Diseases named in the same sentence as PRKCE in open-access papers (continued):
Sharing a sentence is not in itself a finding about the gene and the disease.
type 2 diabetes mellitus (3 papers, 2020 to 2021). A type of diabetes mellitus that is characterized by insulin resistance or desensitization and increased blood glucose levels. "From this information, it can be considered for the analysis if hsa-miR-933 can regulate the overexpressed PEA15, downregulated BDNF, or other ATF2 target genes (PRKACB, GNAS, PRKCE, and MAP4K4) to control type II diabetes mellitus." (PMID 32993798, 2020). "The target genes that were significantly enriched for the development of type II diabetes mellitus in both modules are GNAS, PRKACB, PRKCE, MAP4K4, PEA15, and BDNF." (PMID 32993798, 2020). "In this context, it can be considered if hsa-miR-933 can also regulate MAP4K4 or other protein kinases (PRKCE, PRKACB) to control type II diabetes mellitus." (PMID 32993798, 2020). "Our approach delineated that hsa-miR-933 might control the hyperglycemic condition and hyperinsulinism by regulating ATF2 target genes MAP4K4, PRKCE, PEA15, BDNF, PRKACB, and GNAS which can otherwise lead to the development of type II diabetes mellitus." (PMID 32993798, 2020).
brain ischemia (2 papers, 2016 to 2021). Diminished or absent blood supply to the brain caused by obstruction (thrombosis or embolism) of an artery resulting in neurologic damage. "Nevertheless, PRKCE activation has a protective role in cardiac and brain ischemia while its aberrant activation induces cell proliferation, disruption of cell–cell contacts, tumor progression and metastasis." (PMID 33931671, 2021). "We wanted to determine whether SIRT5 is activated by protein kinase C epsilon (PKCε)-mediated increases in mitochondrial Nampt and whether SIRT5 regulates mitochondrial bioenergetics and neuroprotection against cerebral ischemia." (PMID 27435822, 2016).
glioma (2 papers, 2016 to 2017). A benign or malignant brain and spinal cord tumor that arises from glial cells (astrocytes, oligodendrocytes, ependymal cells). "The effect of miR-34a-5p overexpression on the endogenous protein level of PRKCE was not further tested, because Zhao and colleagues already showed the regulation of PRKCE by miR-34a-5p in glioma endothelial cells." (PMID 27144431, 2016).
lung adenocarcinoma (2 papers, 1992 to 2023). A carcinoma that arises from the lung and is characterized by the presence of malignant glandular epithelial cells. "We found that protein kinase C epsilon is rapidly increased in the human lung adenocarcinoma cell line A549 following irradiation." (PMID 1329908, 1992).
melanoma (2 papers, 2007 to 2022). A malignant, usually aggressive tumor composed of atypical, neoplastic melanocytes. "In the present study, we first screened for any differences in the mRNA expression of the genes encoding these five PKC isozymes (PRKCD, PRKCA, PRKCB, PRKCE and PRKCI) between the BRAFi-sensitive and BRAFi-R melanoma cell lines." (PMID 36551563, 2022). "Additionally, protein kinase C epsilon is expressed in many human melanoma cell lines, and has been hypothesized to be advantageous for in vivo growth of melanoma cells." (PMID 17207277, 2007). "A375-R1 and A375-R2 melanoma cells exhibited significantly increased expression of PRKCA, PRKCE and PRKCI compared to their BRAFi-sensitive counterpart." (PMID 36551563, 2022).
myocardial infarct (2 papers, 2017 to 2019). "Treatment of HDGF recombinant protein reduces apoptosis and oxidative stress in vitro which in turn can decrease myocardial infarct size in an in vivo mouse model in a protein kinase C epsilon- (PKCε-) dependent fashion." (PMID 29358952, 2017).
Obesity (2 papers, 2010 to 2021). Accumulation of substantial excess body fat. "This included protein kinase C elipson (PRKCE), known to be involved in brain tumors, carnitine palmitoyltransferase I (CPT1A), 11β-hydroxysteroid dehydrogenase type 1 (HSD11B1) and apolipoprotein B (APOB) which are all linked to obesity." (PMID 20502671, 2010). "PRKCE has been proven to be a critical DEG in NAFLD, and the expression level and DNA methylation of PRKCE and IGFBP2 were altered in obesity-derived NAFLD." (PMID 34419146, 2021).
acute kidney injury (1 paper, 2024). Sudden and sustained deterioration of the kidney function characterized by decreased glomerular filtration rate, increased serum creatinine or oliguria. "Our study demonstrated that increased PRKCE expression levels correlate with lower eGFRcrea, while recent research suggests that inhibiting PKC-ε signaling could prevent hypoxia-induced acute kidney injury (AKI), indicating that suppressing PRKCE expression might offer renal protective effects." (PMID 38892221, 2024).
anaplastic astrocytoma (1 paper, 2022). "For instance, PKCε (Protein Kinase C epsilon) overexpression in human anaplastic astrocytoma and GBM cases seems to consort constitutive activation of STAT3 through serine 727 phosphorylation." (PMID 35409080, 2022).
B-cell acute lymphoblastic leukemia (1 paper, 2025). A neoplasm of lymphoblasts committed to the B-cell lineage, typically composed of small to medium-sized blast cells. "Recently, Chen et al54 uncovered a carcinogenic role for phosphorylated TET1 in B-cell acute lymphoblastic leukemia, driven by protein kinase C epsilon (PRKCE) and ataxia-telangiectasia mutated (ATM) kinases." (PMID 40520993, 2025).
bipolar disorder (1 paper, 2012). A disorder of the brain that causes unusual shifts in mood, energy, activity levels and the ability to carry out day-to-day tasks. "Lithium, the primary therapeutic choice for bipolar disorder, has been shown to decrease the levels of PRKCE, a mechanism that could be involved in the therapeutic effect of this drug." (PMID 22389694, 2012).
cardiac hypertrophy (1 paper, 2019). "MiR-31 could promote cardiac hypertrophy through targeting protein kinase C epsilon (PKCε), which has been shown to blunt cardiac pathophysiologic responses in response to chronic hypoxia by a HIF-1a-mediated mechanism." (PMID 31208080, 2019).
cervical cancer (1 paper, 2023). A primary or metastatic malignant neoplasm involving the cervix. "The results of this study have suggested that variants rs1553369874 and rs1345511001 in PRKCE are associated with risk of cervical cancer susceptibility in Pakistani population." (PMID 37667176, 2023). "The present study has explored the role of missense variants in PRKCE in association with cervical cancer in Pakistani female population." (PMID 37667176, 2023). "These PRKCE variants may contribute towards the risk of cervical cancer in various population, as similar SNPs have been corelated with the risk of cancers in previous studies." (PMID 37667176, 2023). "Genotype analysis of PRKCE non-synonymous variants was performed which indicated that the altered genotype-AA of variant E14K with P-value 0.0001, and altered genotype-CC of variant D39H with P-value 0.045, were associated significantly with the risk of the development of cervical cancer." (PMID 37667176, 2023).
clear-cell renal cell carcinoma (1 paper, 2022). "To further validate the results of the single-cell analysis, we explored the role of PRKCE overexpression in the two clear-cell renal cell carcinoma cell lines." (PMID 36186442, 2022).
COVID-19 (1 paper, 2023). A disease caused by infection with severe acute respiratory syndrome coronavirus 2. "PRKCE was also upregulated in nasopharyngeal swabs from COVID-19 patients." (PMID 38002279, 2023).
diabetes (1 paper, 2017). "This relationship between growth-related factors and diabetes and bone metabolism could explain the association of PRKCE with conformation traits." (PMID 28118822, 2017). "PRKCE is a well-known key factor in cell proliferation and differentiation, muscle contraction, gene expression, cell growth and apoptosis, metabolism and diabetes, as reviewed by Akita and Geraldes and King." (PMID 28118822, 2017). "However, overexpression of PRKCE results in malignant tumors and diabetes." (PMID 28118822, 2017).
follicular lymphoma (1 paper, 2021). Follicular lymphoma is a form of non-Hodgkin lymphoma characterized by a proliferation of B cells whose nodular structure of follicular architecture is preserved. "Further studies on transcriptomics profiling also confirmed that PRKCE is a specific biomarker to identify follicular lymphoma, one of the major subtypes of non-Hodgkin lymphoma, reflecting the specific association between PRKCE and lymphoma." (PMID 34899868, 2021).
gastric cancer (1 paper, 2016). A primary or metastatic malignant neoplasm involving the stomach. "The PRKCE (Protein Kinase C, Epsilon) is a key element in EGFR signaling pathway (annotation by KEGG), which promotes the proliferation of gastric cancer cells in response to hypoxia." (PMID 26872056, 2016).
Glucose intolerance (1 paper, 2013). Glucose intolerance (GI) can be defined as dysglycemia that comprises both prediabetes and diabetes. "We have previously shown that deletion of protein kinase C epsilon (PKCε) in mice results in protection against glucose intolerance caused by a high fat diet." (PMID 23469261, 2013).
head and neck cancer (1 paper, 2022). A primary or metastatic malignant neoplasm affecting the head and neck. "Higher levels of PRKCE were found to correlate with an increase in disease recurrence and a decrease in overall survival in head and neck cancer." (PMID 36362284, 2022).
head and neck squamous cell carcinoma (1 paper, 2022). A squamous cell carcinoma that arises from any of the following anatomic sites: lip and oral cavity, nasal cavity, paranasal sinuses, pharynx, larynx, and salivary glands. "Targeted disruption of PRKCE has been shown to reduce cell invasion and motility through inactivation of RhoA and RhoC GTPases in head and neck squamous cell carcinoma." (PMID 36362284, 2022).
heart failure (1 paper, 2022). Inability of the heart to pump blood at an adequate rate to meet tissue metabolic requirements. "In a heart failure rat model, dofetilide attenuated isoprotenerol-induced heart failure by correcting the abnormal expression of the calcium handling FK506 binding protein, NADPH oxidase and protein kinase C epsilon signaling pathway." (PMID 36362438, 2022).
Hyperinsulinemia (1 paper, 2020). An increased concentration of insulin in the blood. "Insulin itself can create a positive feedback loop by activating ATF2 in this pathway solely or mediated by MAPK8 (preceded by MAP4K4) or PRKCE which can eventually lead to hyperinsulinemia." (PMID 32993798, 2020).
ischemia (1 paper, 2022). A hypoperfusion of the BLOOD through an organ or tissue caused by a PATHOLOGIC CONSTRICTION or obstruction of its BLOOD VESSELS, or an absence of BLOOD CIRCULATION. "Another novel PKC isozyme, PKCε, is encoded by the PRKCE gene and is involved in ischemia tolerance following ischemic preconditioning and ischemia injury." (PMID 35141226, 2022).
kidney cancer (1 paper, 2022). Primary or metastatic malignant neoplasm involving the kidney. "The Oncomine database indicated that PRKCE mRNA levels were significantly lower in most human cancers, including kidney cancer." (PMID 36186442, 2022). "Moreover, the CCLE dataset analysis also showed that PRKCE methylation negatively correlated with PRKCE expression in various cancer cells, including kidney cancer cells (R = -0.13, p < 0.001)." (PMID 36186442, 2022).
kidney tumor (1 paper, 2022). "Additionally, PRKCE was generally lower in many tumor cell lines, including kidney tumor cell lines." (PMID 36186442, 2022).
lymphoma (1 paper, 2021). A malignant (clonal) proliferation of B- lymphocytes or T- lymphocytes which involves the lymph nodes, bone marrow and/or extranodal sites. "Analytical results indicated that some inferred genes, such as RAC3, TEC, IRAK2/3/4, PRKCE, SMAD3, BLK, TXK, PRKCQ, were associated with the initiation and progression of lymphoma." (PMID 34899868, 2021). "The analytical results showed that some of these genes (RAC3, TEC, IRAK2/3/4, PRKCE, SMAD3, BLK, TXK, PRKCQ) could be novel lymphoma-associated genes." (PMID 34899868, 2021).
papillary thyroid carcinoma (1 paper, 2020). "Moreover, PRKCE has also reported being abundantly expressed in papillary thyroid carcinoma." (PMID 32869841, 2020).
prediabetes (1 paper, 2021). "Similarly, the key lncRNAs were ENST00000462720 and ENST00000480633, and the corresponding mRNA was PRKCE between T2DM and prediabetes patients." (PMID 35140684, 2021).
pulmonary carcinoid tumours (1 paper, 2021). "A recent study, however, reports a novel fusion transcript derived from a chromosomal translocation between the TRIB2 and the PRKCE genes, the latter coding for protein kinase C epsilon in pulmonary carcinoid tumours." (PMID 34070799, 2021).
sensitization (1 paper, 2024). "Skin denervation may induce nerve sensitization, which consequently results in chronic pain through the activation of protein kinase C epsilon (PKCε)." (PMID 37906389, 2024).
SHORT syndrome (1 paper, 2022). A rare disorder characterized by multiple congenital anomalies, including short stature, hyperextensibility of joints, ocular depression, Rieger anomaly and teething delay in which the cause of the disease is a mutation in PIK3R1 gene. "Hereditary insulin resistance syndromes include genetic syndromes caused by INSR mutations, SHORT syndromes caused by PIK3R1 abnormalities, and conditions caused by AKT2, TBC1D4, or PRKCE abnormalities." (PMID 36626508, 2022).
triple-negative breast carcinoma (1 paper, 2020). An invasive breast carcinoma which is negative for expression of estrogen receptor (ER), progesterone receptor (PR), and human epidermal growth factor receptor 2 (HER2). "Consistently, a recent study has found the up-regulated PRKCE in triple-negative breast cancers." (PMID 32869841, 2020).
cancer (26 papers, 2011 to 2023). A tumor composed of atypical neoplastic, often pleomorphic cells that invade other tissues. "Genetic variants in PRKCE alter the structure and functions of the protein, ultimately leading towards cancer." (PMID 37667176, 2023). "Based on evidence that nsSNPs in other PKC isoforms are correlated with the risk of cancers, we examined the association of a non-synonymous SNP (snSNP) in PRKCE, i.e. rs1553369874, in HCV-induced HCC in Pakistani population." (PMID 36782184, 2023). "Genetic variants in PRKCA (rs9909004), PRKCQ (rs571715), PRKCI (rs546950 and rs4955720), PRKCG (rs3745406), PRKCD (rs2306574), PRKCH (rs2230500), PRKCE (rs940052) have shown an association with the progression of different types of cancers 10−14." (PMID 36299231, 2022). "This study provides foundations for further studies related to exploring PRKCE as a potential diagnostic marker for human diseases, especially cancers." (PMID 36299231, 2022). "Our analysis in silico further suggests that both miRNAs (-31 and -200a) target other cancer-associated genes such as protein kinase C epsilon (PRKCE)." (PMID 26379276, 2015). "Studies have demonstrated that PRKCE non-synonymous variants rs1553369874 and rs1345511001 might have a damaging role leading to cancer susceptibility." (PMID 37667176, 2023). "PRKCE variations that are found to be associated with cancer stage and metastasis may also impact its interaction with other signaling proteins, leading to cancer progression." (PMID 36672978, 2023). "Fourth, protein kinase C epsilon gene (PRKCE) is overexpressed in most solid tumors and plays critical roles in different cancer-associated pathways, including toll-like receptor 4 (TLR-4) signaling that plays a role in the induction of both innate and adaptive immunity." (PMID 35013211, 2022). "PRKCE plays essential roles in the regulation multiple cellular processes linked to cytoskeletal proteins, functions in ion channel regulation, and is involved in cancer cell invasion and regulation of apoptosis." (PMID 35851595, 2022). "To better explore the functions of PRKCE in cancer, we constructed the gene-gene interaction network for PRKCE and the altered neighboring genes using Gene MANIA." (PMID 36186442, 2022). "We also applied the Oncomine database and TIMER to analyze the expression levels of PRKCE across different cancer types." (PMID 36186442, 2022). "Mounting evidence has highlighted the key role of PRKCE in the initiation and development of several types of human cancer, including kidney renal clear cell carcinoma (KIRC)." (PMID 36186442, 2022). "Recent studies have revealed that PRKCE is an anti-apoptotic gene that is commonly upregulated to promote the survival of different types of cancer." (PMID 35088239, 2022). "Consistently, from four KIRC studies of the GEO database, PRKCE was expressed lowly in KIRC compared to non-cancer tissues." (PMID 36186442, 2022). "We used cox proportional hazards models to investigate the effect of PRKCE on cancer prognosis in 33 cancer types." (PMID 36186442, 2022). "According to the recently reported study, PRKCE is an anti-apoptotic gene that is often down-regulated to promote the survival of different types of cancers." (PMID 32869841, 2020). "Chronic hypoxia induced GRP78 in human cancer cells possibly through the protein kinase C-epsilon/ERK/AP-1 signaling cascade." (PMID 30931255, 2019). "Our comprehensive gene expression analysis of all PKC isoforms revealed that three of the nine PKC coding genes (PRKCB, PRKCD and PRKCE) showed a down-regulation greater than two in the cancer tissue, while only one of the genes (PRKCG) was up-regulated." (PMID 26989024, 2016). "The over-expression of IPS-1 downregulated the anti-apoptotic genes such as BCL2, BIRC3 and PRKCE, known to promote survival in different types of cancer." (PMID 25950488, 2015).
cancer (continued). "Protein kinase C epsilon (PKCε), an oncogene overexpressed in several human cancers, is involved in cell proliferation, migration, invasion, and survival." (PMID 21955404, 2011). "KEGG pathway functional annotations indicated that PRKCE was involved in the chemokine signaling pathway (p = 1.37e-11), T cell receptor signaling pathway (p = 1.52e-11), and PD-L1 expression and PD-1 checkpoint pathway in cancer (p = 6.37e-08)." (PMID 36186442, 2022). "Protein kinase C ε (PRKCE) is a gene correlated to tumor aggressiveness and has been reported to be involved in malignant transformation and metastasis as it is up-regulated in various cancers, such as mammary and lung cancer." (PMID 32869841, 2020). "Additionally, the KEGG pathway analysis revealed that PRKCE is involved in the pathway of MicroRNAs in cancer, the cGMP-PKG signaling pathway, and pathway of vascular smooth muscle contraction." (PMID 29636077, 2018). "Also, we predicted that PRKCA, PRKCD, and PRKCE might be involved in improving the response of many cancers to PD-L1 blocking-dependent immunotherapies, but their effect on HLA-dependent therapies may run in line with their effect on the TILs aggregation." (PMID 35174160, 2021). "Moreover, PRKCE promotes cancer development by acting as an anti-apoptotic gene." (PMID 32869841, 2020). "Collectively, the expression levels of PRKCI and PRKCG were elevated in most of the significantly compared cancers, while PRKCA, PRKCB, PRKCE, and PRKCQ tended to be downregulated among most cancer types." (PMID 35174160, 2021). "Otherwise, the correlations between PRKCA, PRKCD, PRKCE, and PRKCG expressions and the infiltration of the immune cells varied between cancer types." (PMID 35174160, 2021). "For PRKCA, PRKCD, PRKCE, and PRKCG, the correlation between their expressions and HLAs enrichment scores were variable among different cancers." (PMID 35174160, 2021). "PRKCE, also known as PKC ε, is a novel member of the PKC isozyme family involved in the regulation of complex cellular processes in diverse cancers, as a paramount bridge between protein networks." (PMID 31285693, 2019). "We found the selective upregulation of TRAIL and downregulation of BCL2, BIRC3 and PRKCE in the MDAMB-231 cancer cells but not in the MCF10A cells." (PMID 25950488, 2015).